DENND5A (DENN domain containing 5A)
Description:
Guanine nucleotide exchange factor (GEF) which may activate RAB6A and RAB39A and/or RAB39B. Promotes the exchange of GDP to GTP, converting inactive GDP-bound Rab proteins into their active GTP-bound form. Involved in the negative regulation of neurite outgrowth (By similarity).
Synonyms: Rab6IP1; KIAA1091; FLJ22354; FLJ33829; FLJ43455; DEE49; EIEE49
Tractability: PROTAC: ubiquitination databases record sites on it; its protein half-life has been measured.
Gene: Protein-coding gene on chromosome 11 (9,138,825 to 9,265,959, reverse strand). Ensembl gene ENSG00000184014.
Subcellular location: Golgi apparatus membrane
Subcellular location (Human Protein Atlas): Golgi apparatus; Vesicles
Pathways (Reactome):
Vesicle-mediated transport: RAB GEFs exchange GTP for GDP on RABs
Gene Ontology:
Molecular function: guanyl-nucleotide exchange factor activity; protein binding; small GTPase binding
Biological process: retrograde transport, endosome to Golgi; negative regulation of neuron projection development
Cellular component: retromer complex; trans-Golgi network; cytosol; Golgi membrane
Genetic constraint (gnomAD): Loss-of-function variants: 55 observed, 119.88 expected, observed/expected ratio (o/e) 0.46, 90% interval 0.37 to 0.57. The upper end of that interval is the gene's LOEUF score, 0.57, which puts it in group 2 of 6, group 1 being the genes least tolerant of losing a copy. Missense variants: 1,178 observed, 1,520.2 expected, observed/expected ratio (o/e) 0.77, 90% interval 0.74 to 0.81. Synonymous variants: 571 observed, 589.46 expected, observed/expected ratio (o/e) 0.97, 90% interval 0.9 to 1.04.
Homologues: Orthologues: chimpanzee DENND5A (99% identical), macaque DENND5A (99% identical), dog DENND5A (99% identical), mouse Dennd5a (98% identical), rat Dennd5a (98% identical), rabbit DENND5A (96% identical), pig DENND5A (95% identical), guinea pig DENND5A (89% identical), tropical clawed frog dennd5a (88% identical), zebrafish dennd5a (83% identical). Paralogues in human: DENND5B (71% identical), PKD1 (17% identical), PKD1L2 (13% identical), PKDREJ (13% identical), PKD1L1 (12% identical), LOXHD1 (11% identical), PKD1L3 (9% identical), PKD2 (8% identical), PKD2L1 (7% identical), PKD2L2 (6% identical).
Diseases named in the same sentence as DENND5A in open-access papers:
DENND5A is named in the same sentence as 11 diseases in open-access papers, as found by Europe PMC text mining. Sharing a sentence is not in itself a finding about the gene and the disease. The quoted sentences say what the papers report.
Epileptic encephalopathy (3 papers, 2022 to 2023). A condition in which epileptiform abnormalities are believed to contribute to the progressive disturbance in cerebral function. "There are reports that mutations in the gene encoding the DENND5A protein are associated with early childhood epileptic encephalopathy." (PMID 36675318, 2023). "Epileptic encephalopathy caused by recessive loss-of-function (LoF) mutations have been reported in DENND5A." (PMID 36539902, 2022).
colorectal cancer (1 paper, 2014). A primary or metastatic malignant neoplasm that affects the colon or rectum. "We report here that three genes, AVL9, DENND5A and NUPL1, which are recurrently deleted in colorectal cancer, all contribute to epithelial morphogenesis." (PMID 25621300, 2014).
leukemia (1 paper, 2021). A malignant (clonal) hematologic disorder, involving hematopoietic stem cells and characterized by the presence of primitive or atypical myeloid or lymphoid cells in the bone marrow and the blood. "Among the variants that are significantly different between leukemia cells and normal cells, chr1:11055657;T>C on SRM and chr11:9173222;A>C on DENND5A are two mutations distributed in all leukemia cell subpopulations and might play an important role in early leukemogenesis." (PMID 33408321, 2021).
tumor (3 papers, 2014 to 2025). "The first was a group of novel genes and the second was a group of genes associated with various cancer and tumour diseases (TXNDC12, NRDC, MIR761, ITSN2, NCOA1, SCUBE2, DENND5A, RCN2)." (PMID 40003092, 2025).
cancer (2 papers, 2014 to 2025). A tumor composed of atypical neoplastic, often pleomorphic cells that invade other tissues. "AVL9, DENND5A and NUPL1 are among the cancer driver candidate genes previously identified via dog-human comparison, and may function in epithelial cell polarity as indicated by bioinformatics analysis." (PMID 25621300, 2014).
colonic polyps (1 paper, 2014). "Significantly, DENND5A-knockdown yields cysts with cells actively growing into the lumen, resulting in a phenotype resembling human colonic polyps." (PMID 25621300, 2014).
DENND5A also shares sentences with these, for which no sentence is quoted: Allergy (1 paper); breast carcinoma (1); cyst (1); gastric cancer (1); infantile epileptic encephalopathy (1).